SIRT7 (sirtuin 7)
Diseases named in the same sentence as SIRT7 in open-access papers (continued):
Sharing a sentence is not in itself a finding about the gene and the disease.
cancer (130 papers, 2006 to 2026). A tumor composed of atypical neoplastic, often pleomorphic cells that invade other tissues. "SIRT7 deficiency disrupts metabolic homeostasis, accelerates aging, and predisposes to inflammatory disorders, cancer, and cardiovascular diseases." (PMID 40636259, 2025). "The expression of SIRT7 is linked to cellular proliferation and is upregulated in conditions like cancer, while it is reduced in cardiovascular and bone diseases." (PMID 40710366, 2025). "As an enzymatically active transcription factor, SIRT7 expression is closely linked to tumor clinicopathological features and patient prognosis, making it a potential target for cancer therapy." (PMID 40165597, 2025). "Mechanistically, SIRT7 deacetylates histone H3 at lysine 18 (H3K18Ac), a marker associated with aggressive tumors, suppressing tumor suppressor genes and promoting cancer cell proliferation and survival." (PMID 40165597, 2025). "Intriguingly, SIRT7 has been increasingly implicated in promoting resistance to anti-cancer therapies that induce DNA damage, positioning it as a potential therapeutic target to overcome drug resistance." (PMID 41471367, 2025). "Together, these findings indicate that reduced SIRT7 expression promotes genomic instability, thereby increasing susceptibility to cancer development in response to environmental stressors." (PMID 41471367, 2025). "Mounting evidence supports that loss of SIRT7 promotes cancer metastasis, resistance to chemotherapy, and tumor survival under energetic stress." (PMID 37676263, 2024). "SIRT7-mediated stabilization of USP39 enables SIRT7 to orchestrate the expression of genes implicated in tumorigenesis, thus effectively fostering cancer progression." (PMID 38383727, 2024). "The emerging role of SIRT7 as a multifaceted player in cancer highlights its significance as a potential diagnostic marker, prognostic indicator, and therapeutic target." (PMID 38383727, 2024). "Elevated SIRT7 expression is often associated with poor prognosis in cancers such as breast and liver cancer." (PMID 39682281, 2024). "SIRT7, the most recently discovered sirtuin, is implicated in the cellular transformation from benign to malignant within cancer cells." (PMID 39404407, 2024). "SIRT7 is a NAD+-dependent histone deacetylase that plays critical roles in human cancer by modulating key processes linked to cell fate determination and oncogenesis such as genome stability, DNA damage repair, and apoptosis." (PMID 36678616, 2023). "Altered SIRT7 expression is frequently observed in human cancers and high SIRT7 is associated with an aggressive cancer phenotype and poor clinical outcomes." (PMID 36678616, 2023). "Together, these findings suggest the possibility that SIRT7 deficiency plays beneficial roles in aging-associated metabolic disorders, cancer, and even lifespan." (PMID 36429037, 2022). "In particular, SIRT7 is also implicated in human cancer by modulating key processes linked to cell fate determination and oncogenesis such as genome stability, DNA damage repair, and apoptosis." (PMID 35174171, 2021). "Altered SIRT7 expression is frequently observed in many human cancers, and high SIRT7 is associated with aggressive cancer phenotype, distance metastasis, and poor survival." (PMID 35174171, 2021). "For example, SIRT7 was identified as a suppressor of MYC function, however, SIRT7 is essential in maintaining low levels of H3K18ac in cancer cells that is associated with poor clinical outcome." (PMID 32117717, 2020). "Knockdown of SIRT7 influences cell cycle control and causes an increased proportion of cancer cells that remain in the G1/S phase." (PMID 31196136, 2019). "First, SIRT7 deacetylates H3K18Ac, whose depletion is associated with highly malignant cancers and poor patient prognosis." (PMID 30510540, 2018).
cancer (continued). "Together, these datademonstrate that increased SIRT7 expression is specifically associated withhuman cancer metastasis." (PMID 25923013, 2015). "SIRT7 is significantly overexpressed in various cancers and is associated with cancer progression." (PMID 39497715, 2024). "This suggests that SIRT7 could significantly influence signaling cascades inherently linked to cancer progression by governing the stability of specific subsets of RNA." (PMID 38383727, 2024). "SIRT7 has since been linked to advanced tumor stages and high-histological grade tumors that metastasize to lymph nodes and distant sites and to worse prognosis and poor survival in breast, liver, colorectal, pancreatic and prostate cancers." (PMID 37676263, 2024). "Because of the previous association of SIRT7 with the pathogenesis of cancer, this data indicates that the role of SIRT7 in cancer may depend on its interaction with other factors." (PMID 38234684, 2023). "Emerging evidence has also implicated SIRT7 in cancer biology." (PMID 35174171, 2021). "A number of recent publications have also implicated SIRT7 in various aspects of cancer biology." (PMID 31196136, 2019). "Here, we directly associated deacetylase activity of SIRT7 with the aggressiveness of cancer cells since the mutated form of SIRT7, a variant bearing a point mutation in the catalytic site of the protein, did not promote cancer cell migration and invasiveness, unlike the native protein." (PMID 29100388, 2017). "The role of Sirt7 in cancer, an aging-associated disease, is still poorly understood." (PMID 24885964, 2014). "In addition to being involved in the aging process, SIRT7 is also associated with regulating tumor cell apoptosis and DNA damage response, all processes related to cancer, and plays a key role in chromatin regulation, cell transformation programs, and in vivo tumor formation." (PMID 40165597, 2025). "Given that SIRT7 is highly related to stress response, cytoprotective signaling, and immunology, our study provides the proof of a principle that the intervention of SIRT7 might bring progress in diseases associated with injury and inflammation, in addition to cancer." (PMID 36918544, 2023). "SIRT7 is a member of the sirtuin family and has emerged as a crucial player in cancer biology, with a multifaceted role in both tumor-promoting and tumor-suppressing activities." (PMID 41642899, 2026). "This comprehensive pan-cancer analysis of SIRT7 provides a framework for understanding its role in cancer biology and identifies potential therapeutic opportunities for personalized interventions." (PMID 41642899, 2026). "In recent years, extensive research has revealed the multifaceted roles of SIRT7 and its therapeutic potential in human diseases, making it a promising drug target for cancer therapy." (PMID 40165597, 2025). "SIRT7 is an NAD(+)‐dependent H3K18Ac (acetylated lysine 18 of histone H3) deacetylase that stabilizes the transformed state of cancer cells." (PMID 40165597, 2025). "SIRT7 has recently emerged as a versatile regulator of anti-cancer immunity, exerting tumor-type-specific effects through distinct molecular mechanisms." (PMID 41471367, 2025). "SIRT7 is an NAD+-dependent deacylase often deregulated in cancer, which deacetylates either H3 lysine 36 (H3K36) or H3K18 with high specificity within nucleosomes." (PMID 39900593, 2025). "SIRT7 integrates genomic maintenance, oncogenic signaling, and immune regulation into a unified network that shapes cancer progression." (PMID 41471367, 2025). "Sirtuins, or 'longevity proteins', a family of 7 proteins (SIRT1 – SIRT7), are involved in skin pathology, including aging, UV-induced photoaging, and cancer." (PMID 40290806, 2025).
cancer (continued). "Although further research is warranted, it is plausible that SIRT7 influences anti-cancer immunity, at least in part, through the regulation of lipid metabolic pathways in specific cellular contexts." (PMID 41471367, 2025). "Recent findings have uncovered an additional—and previously underappreciated—dimension: SIRT7’s capacity to modulate anti-cancer immunity." (PMID 41471367, 2025). "SIRT7 is overexpressed in multiple cancer types, including bladder, leukemia, prostate, and breast cancer." (PMID 41304967, 2025). "Recent studies have found that SIRT7 plays a vital role in various processes of PCa development, including cancer cell proliferation, differentiation, apoptosis, invasion, and metastasis." (PMID 40165597, 2025). "This review synthesizes current understanding of the dualistic role of SIRT7 in cancer, with particular emphasis on its newly established functions in orchestrating anti-cancer immunity." (PMID 41471367, 2025). "SIRT7‐catalyzed H3K18 deacetylation is linked to oncogenic transformation and cancer cell proliferation." (PMID 39215785, 2025). "HDACs, including SIRT7, are typically overexpressed in cancer cells, enhancing deacetylation, leading to tighter binding of histones to DNA, which is unfavorable for gene transcription." (PMID 40165597, 2025). "In the vast majority of cancers, including those of the liver, lung, prostate, and thyroid, SIRT7 promotes cancer progression." (PMID 41471367, 2025). "Nonetheless, the relevance of this regulatory axis in cancer remains to be clarified and should be carefully considered when assessing the therapeutic potential of SIRT7 inhibitors." (PMID 41471367, 2025). "Increasing evidence indicates that SIRT7 regulates distinct metabolic pathways in both cancer and immune cells, yet the implications of these activities for anti-cancer immunity are only beginning to be elucidated." (PMID 41471367, 2025). "In various cancers, including lung cancer, SIRT7 acts as an oncogene by destabilizing tumor suppressors, leading to the increased expression of pro-tumorigenic genes." (PMID 40710366, 2025). "Given that SIRT7 influences both epigenetics and the malignant phenotype of cancer cells, and considering that epigenetic changes are reversible, SIRT7 presents as an ideal target for cancer therapy." (PMID 40165597, 2025). "Understanding how these molecular circuits are rewired in different tumor settings will be crucial for defining when and how SIRT7 becomes an ally or an adversary in cancer." (PMID 41471367, 2025). "Outside of the nucleolus, SIRT7 is responsible for gene promoter regulation and is especially relevant in cancer, where it is often overexpressed and helps to repress tumor suppressor genes and activate metastatic pathways." (PMID 39900593, 2025). "SIRT7 is a driver of tumor growth and metastasis in various cancers and has been proposed as therapeutic target." (PMID 39900593, 2025). "Paradoxically, ATM can also phosphorylate SIRT7 following anti-cancer drug treatment, inhibiting specific DNA repair pathways and promoting cancer cell survival." (PMID 41471367, 2025). "In contrast, in cancer cells, SIRT7 can repurpose these same mechanisms and inhibit DNA damage-sensing factors, ultimately fostering drug resistance." (PMID 41471367, 2025). "Elucidating this connection will be essential to define the contribution of SIRT7-dependent genome protection to cancer immunobiology." (PMID 41471367, 2025). "Paradoxically SIRT7 functions as a potent pro-tumorigenic factor in most cancers—even in those where it initially counteracts tumor development." (PMID 41471367, 2025). "Overall, the function of SIRT7 in cancer is determined by different target proteins, and the role of SIRT7 in CRC needs further exploration." (PMID 40301349, 2025). "This review revisits the current understanding of SIRT7 in cancer by emphasizing its emerging immunomodulatory functions and influence on the tumor microenvironment." (PMID 41471367, 2025).
cancer (continued). "Our observations suggest roles for SIRT3 and SIRT7, both of which are NAD+‐dependent class III histone deacetylases implicated in various diseases, including cancer." (PMID 39873399, 2025). "The pro-oncogenic effects of SIRT7 are generally well described; however, there are also hints at tumor suppressor activities of SIRT7 at the cancer initiation stage." (PMID 39935431, 2025). "Recently, SIRT7 also emerged as a complex regulator of anti-cancer immunity, indicating a broader involvement of this enzyme in shaping tumor–immune interactions." (PMID 41471367, 2025). "SIRT7 also contributes to the adaptation of cancer cells to various stress conditions such as hypoxia, nutrient deprivation, oxidative stress, and chemotherapeutic drug exposure." (PMID 39479446, 2024). "The roles of SIRT7 in cancer are highly context dependent and have been equally reported to be tumor suppressive and oncogenic." (PMID 37676263, 2024). "Recent research has elucidated the connection between SIRT7 and various pathologies, particularly obesity, cardiovascular diseases, bone disorders, and, notably, cancer." (PMID 39335515, 2024). "Conversely, HDAC1, HDAC10, KAT2A, SIRT6, and SIRT7 were upregulated in 13, 16, 17, 14, and 12 cancer types." (PMID 39906742, 2024). "The overexpression of SIRT7 in these cancers suggests its pivotal role in the regulation of cancer-related genes through epigenetic modifications." (PMID 39335515, 2024). "This complex multi-enzymatic nature of SIRT7 endows it with the ability to interact with a diverse array of molecular targets, thereby influencing multiple pathways involved in cancer progression." (PMID 39682281, 2024). "As a member of the SIRT family, SIRT7 has been reported to affect numerous diseases, such as cancers, cardiovascular disease, inflammation, digestive system diseases, and nervous system diseases." (PMID 39092715, 2024). "Aligning with these discoveries, inhibition of SIRT7 has demonstrated the capability to amplify the impact of cancer immunotherapy that incorporates anti-PD-L1 antibodies." (PMID 38383727, 2024). "According to research, SIRT7 functions as an NAD (+)-dependent deacetylase of histone H3 acetylated lysine 18 (H3K18ac), causing the stabilization of the oncogenic phenotype in cancer cells and facilitating transcriptional repression." (PMID 39719443, 2024). "Given the established association of aberrant RNA transcription and maturation with tumorigenesis, further investigations will unveil the extent of SIRT7’s influence on these processes in the context of cancer." (PMID 38383727, 2024). "SIRT7-mediated deacetylation of H3K18 activates pro-oncogenic processes across different types of cancers by epigenetically silencing the expression of key tumor suppressor genes." (PMID 38383727, 2024). "This network underscores the intricate molecular mechanisms underpinning the functions of SIRT7, particularly its involvement in regulating key cancer-related signaling pathways, such as PTK2 and NFκB." (PMID 39796040, 2024). "Further comprehensive studies are essential to understand the role of SIRT7-mediated regulation of the nucleolus in cancer progression." (PMID 39036727, 2024). "While the complete characterization of the molecular targets of SIRT7 for this activity is yet to be accomplished, the potential impact of SIRT7 on cancer progression through this reaction is evident." (PMID 38383727, 2024). "Collectively, these tumor-inhibitory roles attributed to SIRT7 are mainly tissue specific and context dependent and are of a secondary nature, which warrants more detailed investigation before establishing SIRT7 as a key molecular target in cancer." (PMID 37676263, 2024). "SIRT7 is essential for sustaining the malignant characteristics of cancer cells, and its overexpression in diverse cancer types is highly noteworthy." (PMID 38316768, 2024).
cancer (continued). "The nucleolar enzyme sirtuin 7 (SIRT7) promotes cancer progression in certain malignancies, likely in part by controlling ribosome biosynthesis." (PMID 39036727, 2024). "While other sirtuins, such as SIRT1 and SIRT6, exhibit a similar dual role in cancer, SIRT7 stands out due to distinctive attributes that sharply distinguish it from other family members." (PMID 38383727, 2024). "Nevertheless, beyond its role in fostering the growth and survival of HCC cells, SIRT7 emerges as a pivotal participant in the elicitation of anti-cancer immune responses, which can potentially impede cancer progression." (PMID 38383727, 2024). "In contrast, in specific cancer cell types, SIRT7 appears to promote ribosome biogenesis by stimulating the transcription of active rDNA genes and the maturation of pre-ribosomal RNA (pre-rRNA)." (PMID 38383727, 2024). "SIRT7 is up-regulated in numerous human cancers, stimulating cell cycle progression, survival of cancer cells, and metastasis." (PMID 38870055, 2024). "These insights underscore the possibility of utilizing SIRT7 inhibition to heighten the responsiveness of cancer cells to chemoradiation." (PMID 38383727, 2024). "While SIRT7 remains a promising target for the therapy of cancers, more work is needed to understand the correct pharmacomodulation (i.e., activation or inhibition) that is most beneficial for a patient." (PMID 39404407, 2024). "In line with the observed decline in invasive cancers, SIRT7 depletion heightens the migration and invasion of BCa cells by fostering EMT through dampening E-Cadherin (CHD1) expression." (PMID 38383727, 2024). "Recently, increasing evidence has indicated that SIRT7 expression is altered in various human cancers, indicating its significant and controversial roles in tumor biology." (PMID 38894712, 2024). "As our understanding of SIRT7 functions continues to evolve, unraveling its molecular intricacies within the context of various cancers holds promise for advancing personalized cancer treatments tailored to specific malignancies." (PMID 38383727, 2024). "SIRT7 inhibitor 97491 up-regulates apoptosis via cysteine asparaginase-related proteins and inhibits cancer growth in vivo." (PMID 39479446, 2024). "Although the regulatory role of SIRT7 in CDDP sensitivity in cancer cells is yet to be explored, SIRT7 has been established to be involved in CDDP-mediated kidney injury." (PMID 39719443, 2024). "More importantly, the dysregulated expression or activity of SIRT7 was pivotal in cancer biology, whereas its actual role is tumor type-specific and context-dependent." (PMID 36918544, 2023). "Smestad and colleagues have suggested that chromatin hyper-succinylation, following Sirt7 depletion, interferes with DNA repair activities and sensitizes cancer cells to genotoxic agents impairing their survival." (PMID 37735413, 2023). "SIRT7 is frequently overexpressed in multiple cancer types and has generally been considered an oncogene." (PMID 38234684, 2023). "Elevated SIRT7 levels are frequently observed in human cancers, which correlate with poor clinical outcomes and survival." (PMID 36678616, 2023).